AKT1 (AKT serine/threonine kinase 1)
Diseases named in the same sentence as AKT1 in open-access papers (continued):
Sharing a sentence is not in itself a finding about the gene and the disease.
metabolic syndrome (35 papers, 2009 to 2026). A cluster of metabolic risk factors for CARDIOVASCULAR DISEASES and TYPE 2 DIABETES MELLITUS. "CAMDAKT mice served as a model of the effects of metabolic syndrome as it pertains to mitochondrial AKT1 signaling and displayed a severe cardiomyopathic phenotype." (PMID 37891673, 2023). "At the same time, that of PI3K and AKT1 decreased, and the dyslipidemia, aortic intima, and liver lesions improved to a certain extent, suggesting that CGE can regulate vascular wall cells by regulating the TGF-β/PI3K/AKT1 signaling pathways associated with tissue homeostasis." (PMID 41464973, 2025). "We obtained overlapping genes between Danshen compounds and dyslipidemia, and through a PPI network analysis, key target genes such as JAK2, STAT3, PI3K, AKT1, and TLR4 were acquired." (PMID 39598338, 2024). "The results indicated that quercetin had an excellent binding activity with many targets, including CCND1, HIF1A, MYC, AKT1, and EGFR; therefore, it might be a key compound for the effect against dyslipidemia." (PMID 35722157, 2022).
osteoarthritis (35 papers, 2018 to 2025). A noninflammatory degenerative joint disease occurring chiefly in older persons, characterized by degeneration of the articular cartilage, hypertrophy of bone at the margins and changes in the synovial membrane. "Some studies have shown that the osteophyte formation of OA in AKT1-knockout mice was blocked in the animal model of osteoarthritis." (PMID 35496280, 2022).
head and neck cancer (34 papers, 2007 to 2025). A primary or metastatic malignant neoplasm affecting the head and neck. "Furthermore, the expression of PIK3CA and Akt1 in head and neck cancer based on nodal metastasis status was also investigated." (PMID 41480387, 2025).
endothelial dysfunction (33 papers, 2011 to 2025). In vascular diseases, endothelial dysfunction is a systemic pathological state of the endothelium (the inner lining of blood vessels) and can be broadly defined as an imbalance between vasodilating and vasoconstricting substances produced by (or acting on) the endothelium. "In ECs, downregulation of the insulin receptor-Akt1 signaling pathway leads to endothelial dysfunction and an increase in the entry of inflammatory cells into plaques." (PMID 40144296, 2025). "CPE also prevents the downregulation of the Mas1/AKT1/eNOS pathway, enhancing the vasorelaxant effect through NO production and avoiding endothelial dysfunction in arteriole in the remanent functional kidney." (PMID 39195453, 2024). "In the future, we will further explore the mechanism by which biochanin A can improve endothelial dysfunction by binding to its target proteins AKT1 and TNF-α, to provide theoretical support for the possibility of biochanin A as a clinical therapeutic drug." (PMID 38195507, 2024). "Genetic ablation of Akt1 in high-fat-fed ApoE−/− mice leads to increased atherogenesis and endothelial dysfunction." (PMID 34440804, 2021). "AKT1 was the protein with the highest number of interactions, thereby suggesting that it plays a critical role in biochanin A’s prevention and treatment of endothelial dysfunction." (PMID 38195507, 2024). "Biochanin A possibly prevents endothelial dysfunction via a complex network structure with multiple targets and pathways, among which AKT1, TNF-α, NOS3, ICAM-1, and VCAM-1 may be the key targets, according to network pharmacological analysis results." (PMID 38195507, 2024). "This study indicates that biochanin A can target AKT1 and TNF-α to alleviate endothelial dysfunction induced by IL-6 in Perthes disease, which provides a theoretical basis for the treatment of Perthes disease by using biochanin A." (PMID 38195507, 2024). "The secondary condition for thrombosis is endothelial dysfunction due to the increase in TSS, which leads to endothelial cell dysfunction, resulting in upregulated expression of IKCa2.3, IKCa3.1, AKT1, and P300." (PMID 35563689, 2022).
metastatic tumors (31 papers, 2008 to 2025). "AKT1 mutation status was 99% concordant between primary and metastatic tumors (McNemar P = 0.48), with a prevalence of 5.6% and 4.3%, respectively." (PMID 24520381, 2014). "One of the other 2 patients with increased levels of Akt3 in metastatic tumors had extremely high levels of Akt1 (7.61-fold compared to primary tumors) and Akt2 (4.68-fold compared to primary tumors)." (PMID 34591413, 2021). "One patient harbored an AKT1 E17K mutation in the recurrent tumor, whereas PIK3CA E542K and E88Q mutations were detected in the primary and untreated metastatic tumor samples." (PMID 30898102, 2019). "Mice in oe-AKT1-control group had the heaviest liver or spleen weight due to massive metastatic tumors." (PMID 31772677, 2019). "Akt1 KD mice had the fewest metastatic abdominal tumors, while both Akt2 KD and Akt3 KD mice had greater metastatic disease than control mice." (PMID 27533079, 2016). "Previous studies have postulated that inhibition of Akt1 can lead to an enhanced tumor cell invasiveness and more aggressive metastatic disease." (PMID 27533079, 2016). "Further, to identify the role of the factors in motifs with good predictive power (CDK4/SNHG5/hsa-let-7a-3p and UCA1/AKT1/hsa-miR-125b-1) in the regulation of various metastatic tumors, we used Target Mine web server and selected BH method (Benjamini-Hochberg) for P-value adjustment." (PMID 32703153, 2020). "In metastatic disease, adherent EOC cells transition to a dormant spheroid state, characterized previously by low S473 phosphorylation in AKT1." (PMID 35269443, 2022).
cardiomyopathy (28 papers, 2010 to 2025). A disease of the heart muscle or myocardium proper. "Our GO and KEGG analyses revealed that HECTD4 and MYL2 are associated with cardiomyopathy, suggesting that the connection between AKT1 and the ApoA1 level has a direct connection to CVDs." (PMID 36140721, 2022). "The functional analysis of our data for two new loci (HECTD4 and MYL2) shows that they are associated with cardiomyopathy, suggesting that the association between AKT1 and the ApoA1 level has a direct connection to CVDs." (PMID 36140721, 2022). "Furthermore, GO and KEGG analyses revealed that HECTD4 and MYL2 are associated with cardiomyopathy, suggesting that the association between AKT1 and the ApoA1 level has a direct connection with CVDs." (PMID 36140721, 2022). "For instance, the most cited paper reported that circ-Amotl1, a circular RNA, can physically bind with PDK1 and AKT1, thus promoting the protective nuclear translocation of pAKT, which provides protection against Adriamycin-induced cardiomyopathy." (PMID 38680417, 2024). "This interaction activated AKT1 through phosphorylation and facilitated the nuclear translocation of AKT1 to protect cardiomyocytes in doxorubicin-induced cardiomyopathy." (PMID 33134301, 2020). "Exogenous CO inhalation has been shown to protect mice from cardiomyopathy by modulating signaling through the Akt1 pathway which is dependent on mitochondrial biogenesis." (PMID 30333475, 2018). "Moreover, virus-mediated expression of AKT1 in mouse hearts ameliorated the effects of DOX-induced cardiomyopathy." (PMID 21084725, 2010). "We first investigated whether inhibiting cardiac mitochondrial AKT1 could lead to cardiomyopathy." (PMID 37891673, 2023). "It was also shown to attenuate doxorubicin-induced cardiomyopathy in mice by binding phosphoinositide-dependent kinase 1 (PDK1) and AKT1, resulting in AKT1 phosphorylation and nuclear translocation." (PMID 32748089, 2020).
sarcopenia (27 papers, 2020 to 2025). Progressive decline in muscle mass due to aging which results in decreased functional capacity of muscles. "Indeed, skeletal muscle-specific knockout of Akt1 and Akt2, major isoforms of Akt, results in aging phenotypes such as premature sarcopenia and bone loss with reduced mitochondrial mass and functions, as well as a shortened lifespan." (PMID 39513056, 2024). "Our findings suggest that the active ingredients of Citri Reticulatae Pericarpium, particularly Sitosterol and Hesperetin, have the potential to improve sarcopenia by interacting with AKT1 and MTOR proteins through the PI3K-AKT signaling pathway." (PMID 39519004, 2024). "This highlights the significance of AKT1 in skeletal muscle and suggests the potential impact of AKT activity on Sarcopenia and lifespan." (PMID 37832096, 2023). "Common targets between selected components of ECR detected by HPLC and muscle atrophy/sarcopenia were AKT1, as suggested partly by the present results, and CAV1." (PMID 37834245, 2023). "Seven main active components (Anonaine, Eucalyptol, Neohesperidin, Obovatol, Honokiol, Magnolol, and beta-Eudesmol) and 26 target proteins of MC-sarcopenia, of which 4 were core proteins (AKT1, EGFR, INS, and PIK3CA), were identified." (PMID 35176999, 2022). "Conversely, the activity of AKT1 may promote skeletal muscle mass and, hence, cope with age-related sarcopenia." (PMID 39519004, 2024). "Therefore, we speculate the therapeutic effect of MC on sarcopenia may play a role in the physiological function of AKT1 through Honokiol." (PMID 35176999, 2022). "Furthermore, the results of molecular docking showed that there exists direct hydrogen bondings between the active components (Honokiol, Magnolol, and Obovatol) of MC and the core proteins of sarcopenia (AKT1, EGFR, INS, and PIK3CA), which verifies our analysis and prediction from another angle." (PMID 35176999, 2022). "Subsequently, AKT1 and CAV1 have been identified in the interactions between ellagic acid and sarcopenia or muscle atrophy." (PMID 37834245, 2023). "Then, MC-sarcopenia targets were filtered to obtain four core proteins, namely PIK3CA, AKT1, EGFR, and INS." (PMID 35176999, 2022). "Our findings revealed that AKT1 and MTOR are the crucial targets by which the active ingredients of Citri Reticulatae Pericarpium, particularly Sitosterol and Hesperetin, may act to alleviate sarcopenia through the PI3K-AKT signaling pathway." (PMID 39519004, 2024).
chronic myeloid leukemia (26 papers, 2011 to 2025). "It is displayed that FAM168A might act as a linker protein binding to BCR-ABL1 and AKT1, further enhanced the activity of AKT1/NF-κB signaling pathway, thus, increased of G2/M phase cells and Cyclin B1 level in chronic myeloid leukemia." (PMID 35459265, 2022).
psychosis (26 papers, 2014 to 2025). "Although this exact mechanism is still under research, it has been found that chronic marijuana users who have a specific variant of the AKT1 gene are at an increased risk of developing psychosis." (PMID 36949890, 2023). "Genetic variations in AKT1 facilitate short-term as well as longer-term psychosis effects associated with the use of cannabis." (PMID 37185752, 2023). "In fact, the AKT1 genotype has been shown to influence the risk of psychosis, especially in young cannabis users." (PMID 35447977, 2022). "Three case control studies demonstrated that, depending on frequency of cannabis use, users with the AKT1 C/C genotype had between a two-fold (history of use) and seven-fold (daily use) increased risk in the development of psychosis compared to T/T carriers." (PMID 33526106, 2020). "Three studies have investigated the moderating effect of the AKT1 genotype (rs2494732 locus) on the association between cannabis use and the risk of psychosis." (PMID 32059350, 2020). "All recent studies that have investigated the moderating effect of the AKT1 genotype on the relationship between cannabis and psychosis have concluded that C carriers of the rs2494732 SNP have an increased risk of developing psychosis after cannabis use." (PMID 32059350, 2020). "In summary, evidence exists for a moderating effect of the AKT1 genotype (rs2494732 locus) on the association between cannabis use and the risk of psychosis, with the highest risk for C/C carriers." (PMID 32059350, 2020). "A second multivariable logistic regression adjusting for the potential confounders showed a significant interaction between DRD2/AKT1 and lifetime frequency of cannabis use on risk of psychosis (N=402, likelihood ratio test =11.91; P=0.042)." (PMID 27336035, 2015). "The present results suggest an interaction between DRD2 rs1076560 and AKT1 rs2494732 genotypes on psychosis risk among cannabis users." (PMID 27336035, 2015). "Individuals carrying the DRD2 T allele or the AKT1 C allele have an increased psychosis risk in the context of cannabis use; however, the risk is especially increased in subjects who carry ‘risk’ alleles from both genes." (PMID 27336035, 2015). "Preliminary experimental evidence has also implicated a different polymorphism of the AKT1 gene (the GG genotype of the SNP rs1130233) as a moderator of sensitivity to the acute psychosis-inducing effect of THC." (PMID 24904437, 2014). "A polymorphism (rs2494732) in the AKT1 gene was identified that interacted with the use of cannabis in the pathogenesis of psychosis: carriers of the C/C genotype on rs2494732 were most likely to develop psychotic illness after smoking cannabis." (PMID 24860514, 2014). "AKT1 is another gene thought to play a role in moderating the association between cannabis and psychotic disorders." (PMID 24904437, 2014). "Moreover, exposure of adolescents to THC (particularly those already genetically vulnerable (e.g., COMT Val158Met, AKT1 polymorphisms) increased the risk of psychosis." (PMID 41127784, 2025). "It is proposed to consider limiting or avoiding high doses of THC in patients with positive family histories of psychosis; in situations of increased risk, targeted testing for AKT1 rs2494732 may be useful (clinical evidence of G×E)." (PMID 41465160, 2025). "COMT and AKT1 genes are significant modifiers of cannabis-induced psychosis risk." (PMID 41127784, 2025). "Through its effects on neuronal survival, synaptic plasticity, and network excitability, altered AKT1 activity can modulate dopaminergic and glutamatergic circuit function and has been implicated in the pathophysiology of psychosis and related neuropsychiatric phenotypes." (PMID 41465160, 2025). "In a translational study, the AKT1 genotype rs2494732 predicted the exacerbation of acute psychotic symptoms after naturally smoked cannabis, and an independent case–control study showed an interaction between AKT1 and cannabis use in the risk of first-episode psychosis." (PMID 41465160, 2025).
psychosis (continued). "Moreover, AKT1 was nominated as a marker of the genetic predisposition to psychosis in cannabis users." (PMID 37185752, 2023). "For AKT1, a differentially methylated region associated with a psychosis-related behavioral response overlaps with a binding motif for the well-known activating transcription factor, SP1, and a specific pattern of methylation may interfere with its binding." (PMID 35327363, 2022). "Genetic variation in AKT1 may mediate both short-term as well as longer-term effects on psychosis expression associated with the use of cannabis, possibly through a mechanism of cannabinoid-regulated AKT1/GSK-3 signaling downstream of the DRD2 receptor." (PMID 36135314, 2022). "Moreover, several genotypes moderate the impact of cannabis use on psychosis risk, particularly those involved in the dopamine function, such as AKT1." (PMID 32059350, 2020). "Individuals with polymorphisms of COMT and AKT1 genes may be at increased risk for psychotic disorders in association with cannabinoids, as are individuals with a family history of psychotic disorders or a history of childhood trauma." (PMID 24904437, 2014). "In a sample comprised of 801 patients with psychosis, 740 of their unaffected siblings, and 419 controls, van Winkel showed that cannabis users with the C/C genotype of a specific polymorphism (rs2494732) of the AKT1 gene had a twofold increase in risk of being diagnosed with psychotic disorder." (PMID 24904437, 2014). "Replicated findings include an interaction between a polymorphism in the AKT1 gene and cannabis use in the development of psychosis and an interaction between the length polymorphism of the serotonin transporter gene and childhood maltreatment in the development of persistent depressive disorder." (PMID 24860514, 2014). "The National Institute on Health Abuse suggests that polymorphisms of catechol-O-methyltransferase (COMT) and alpha serine/threonine-protein kinase (AKT1) genes may affect the response to cannabis and predict the possible risk of psychosis and cognitive impairment." (PMID 37185752, 2023). "AKT1 signalling cascade affects dopamine 2 (D2) receptors, encoded by the DRD2 gene, known to play a key role in psychosis and decreased AKT1 expression could result in an increased level of synaptic activation through the inhibitory effects from dopamine binding on the enzyme." (PMID 34573260, 2021). "Polymorphisms in the AKT1 gene may play a role in psychosis induced by early cannabis use." (PMID 25426017, 2014). "This review also looks into the effect of genetic factors, especially the variants of the gene coding the enzymes COMT and AKT1, which interact with THC exposure to modulate psychosis." (PMID 41127784, 2025). "Clinical data indicate a significant role for AKT1 in sensitivity to the acute psychotomimetic effects of THC and in the risk of psychosis in users." (PMID 41465160, 2025). "Translational work shows that the AKT1 rs2494732 variant modulates the acute psychotomimetic response to THC and interacts with cannabis exposure in determining psychosis risk." (PMID 41465160, 2025). "PIK3CA and PIK3CB, two class I subunits of PI3K, as well as AKT1 are thus likely to have influenced the phenotypic expression of autism spectrum disorder and/or psychosis among the 22q11DS patients." (PMID 37872602, 2023). "In reviewing this research, the focus is on three genes as models for differential methylation, MCHR1, AKT1 and TDO2, each of which have been investigated for genetic association with psychotic disorders." (PMID 35327363, 2022). "When studying single candidate genes, AKT1 and COMT have frequently been associated with cannabis use and an increased risk of psychosis." (PMID 32059350, 2020). "The AKT1 rs2494732 CC homozygotes with a history of cannabis use showed a greater than twofold increase in the likelihood of having a psychotic disorder in comparison with the AKT1 rs2494732 TT homozygotes." (PMID 28822116, 2018).